CBX8 (chromobox 8)
Diseases named in the same sentence as CBX8 in open-access papers (continued):
Sharing a sentence is not in itself a finding about the gene and the disease.
tumor (continued). "Accordingly, CBX8 was overexpressed at both mRNA and protein levels in the tumor." (PMID 31495785, 2019). "By contrast, silencing CBX8 in the SMMC-7721 cells markedly decreased tumor volume and weight." (PMID 30718464, 2019). "To explore the potential roles of CBX8 in CRC, we collected several paired fresh tissues, including CRC tumor specimens and the corresponding adjacent non-tumor tissue specimens, and RT-PCR and western blot were performed to measure CBX8 mRNA and protein levels in these tissues." (PMID 25360999, 2014). "CBX8 is overexpressed in HCC tissues compared to normal tissues, correlating with aggressive tumor behavior and shorter survival times." (PMID 40175347, 2025). "Based on the Human Protein Atlas database, immunohistochemical staining of clinical specimens also identified the CBX8 level in LIHC, and OV tumor tissues exceeded compared to adjacent normal tissues." (PMID 35813444, 2022). "The expression of CBX8 in 95 paired human CRC and adjacent non-tumor specimens was determined by quantitative PCR and correlated with the patients’ clinicopathological data." (PMID 35681547, 2022). "Aberrant expression of PcG proteins like BMI1, CBX8, and EZH2 is mainly responsible for the deposition and maintenance of pro-tumor histone modification in HCC." (PMID 36566204, 2022). "The expression of CBX genes differs across solid tumors and for CBX1, CBX2, CBX3, CBX4, CBX5, and CBX8 is predominantly upregulated, while for CBX6 and CBX7 is mostly downregulated in tumor tissues." (PMID 36361869, 2022). "As for protein level, through the CPTAC database, higher CBX8 protein expression was observed in LIHC, KIRC, and OV tumor tissues compared to normal tissues (p < 0.05)." (PMID 35813444, 2022). "In terms of ESCC, CBX8 was demonstrated to promote cell proliferation and invasion but suppress EMT and tumor metastasis by directly binding to the Snail promoter." (PMID 36140750, 2022). "High expression of CBX8 in LSCC patients led to shorter overall survival and correlated with tumor stage and lymphatic metastasis." (PMID 35814427, 2022). "In this analysis, we exhibited that the expression levels of CBX8 were increased in GBM and positively correlated with higher tumor grade and recurrent status." (PMID 35210369, 2022). "Compared with CBX8 and DPY30, CENPT and PDAI1 have been less reported on promoting tumor development by influencing histone modification." (PMID 34090418, 2021). "We also analyzed another cohort (GSE14520) from GEO database and discovered that in comparison with non-tumor tissues, HCC lesions exhibited higher levels of CBX8 mRNA." (PMID 31495785, 2019). "We also examined the potential correlation of CBX8 expression with HCC disease parameters and tumor morphology." (PMID 30718464, 2019). "Additionally, CBX8 activates the AKT/β-catenin signaling pathway by upregulating EGR1 and miR-365-3p, further driving tumor progression and metastasis in HCC cell lines and in vivo." (PMID 40175347, 2025). "Mechanistically, CBX8 interacts with Y-box binding protein 1 (YBX1) to regulate the cell cycle through modulation of Cyclin D1 expression, thereby promoting proliferation in SK-Hep-1, Huh7, and MHCC-97H cells and supporting tumor development in mouse models." (PMID 40175347, 2025). "Then we injected the stable cell lines containing m3E sgRNAs for CBX8, CCND1, PTP4A3, RPS6KA5 and TNFSF10 into nude mice and checked whether tumor growth was repressed." (PMID 38012744, 2023). "We believe the high expression of CBX8 in NAT is not just a biomarker but is one of the factors contributing to tumor progression, recurrence and metastasis." (PMID 35681547, 2022). "Here, CBX8 mRNA showed a significant increase between tumor and normal conditions in pRCC but not in ccRCC." (PMID 36292141, 2022). "Subgroup analyses exhibited that CBX8 expression in nontumor groups was lower compared to tumor tissues of LIHC and OV patients in phases I-II (p < 0.05)." (PMID 35813444, 2022).
tumor (continued). "Collectively, our results allowed the decipherment of a functional axis whereby KPNA2 assisted the nuclear import of CBX8 to activate downstream effectors by recruiting BCOR to the promoter region of PRDM1, thus highlighting the tumor-promoting properties of KPNA2 in BCa." (PMID 33731128, 2021). "On the other hand, inhibition of CBX8 in T24 cells could counterbalance the pro-tumor effects of KPNA2, suggesting that the oncogenic role of KPNA2 in BCa was dependent on CBX8." (PMID 33731128, 2021). "However, high CBX8 expression is related to a low rate of tumor metastasis and a favorable prognosis in CRC patients, and the downregulated CBX8 expression inhibits CRC proliferation." (PMID 34117289, 2021). "The expression of KPNA2 and CBX8 was correlated with the pathological grade, clinical stage, metastasis, and recurrence of the tumor (p < 0.05), but not correlated with age, gender, smoking history, and gross hematuria (p > 0.05)." (PMID 33731128, 2021). "Furthermore, there was a clear inverse relationship between CBX7 and CBX8 (and to a minor extent CBX2) mRNA expression levels of tumor and normal samples in the TCGA tumor data set overexpressing miR-375." (PMID 27449098, 2016). "The results show that repression of m3Es proximal to CBX8 (m3eCBX8) and RPS6KA5 (m3eRPS6KA5) caused significant inhibition of tumor volume and weight; and repression of m3eTNFSF10 caused significant reduction of tumor weight but not tumor volume." (PMID 38012744, 2023). "Our study found that in LIHC patients, CBX8 expression was obviously higher in stages II-III than in stage I. In KIRC patients, CBX8 expression was obviously higher in stage IV than in stage I, suggesting that CBX8 can be a supervision index for distant tumor metastases in LIHC and KIRC." (PMID 35813444, 2022). "Understanding the functional significance of the reciprocal expression pattern of CBX8 relative to CBX6 and CBX7 in GBMs might eventually leads to the development of compounds targeting the chromodomain of a specific CBX protein which potentially have anti-tumor efficacy." (PMID 24260522, 2013). "Our findings show that CBX3, CBX4, and CBX8, all members of the polycomb (Pc) group of the non-canonical PRC1 (nPRC1) complex, are significantly upregulated in both CRC cell lines and tumor tissues." (PMID 40806514, 2025). "Higher CBX8 gene expression was discovered in LIHC, KIRC, and OV tumor tissues than nontumor tissues, following many studies." (PMID 35813444, 2022). "Compared with their non-tumor counterparts, CBX8 mRNA and protein levels were significantly elevated in CRC tumor tissues." (PMID 25360999, 2014). "Furthermore, gene set enrichment analysis indicated that neoplasm metastasis and invasion, cell movement, mammary stem cell, and BMP4-related gene signatures were significantly enriched in CBX8-overexpressing cells (data not shown)." (PMID 30718464, 2019). "Therefore, CBX8, c-Myc and cyclin A2 are most likely not good therapeutic targets; however, they are able to promote proliferation even while their inhibition may enhance metastasis, indicating that current strategies mainly targeting proliferation may have undesirable effects on tumor progression." (PMID 25360999, 2014). "Furthermore, using DLD1 cell line, which has lower CBX8 protein level compared with other CRC cell lines, the cell viability was not changed when CBX8 was stably overexpressed in this cell line in vitro, and the CRC xenograft tumor growth of this stable transfectant was not impaired neither in vivo." (PMID 25360999, 2014).
CBX8 also shares sentences with these, for which no sentence is quoted: infection (5 papers); cyst (2); diffuse large B-cell lymphoma (2); acute leukemia (1); B-cell lymphoma (1); degenerative diseases (1); dengue virus infection (1); infectious disease (1); leiomyoma (1); lymphoid neoplasm (1); lymphopenia (1); oral cancer (1); ovarian serous cystadenocarcinoma (1); pancreatic adenocarcinoma (1); paraganglioma (1); pheochromocytoma (1); sarcoma (1); skin cutaneous melanoma (1); testicular germ cell tumor (1); thymoma (1); uterine carcinoma (1); uterine carcinosarcoma (1); viral infection (1).